DCN (decorin)
Diseases named in the same sentence as DCN in open-access papers (continued):
Sharing a sentence is not in itself a finding about the gene and the disease.
cancer (continued). "Since no standard ofCS-CD44, ofCS-SDC1, and ofCS-CSPG4 are available, the sensitivity and specificity of the optimized ELISA were characterized by cancer cell line (SW480) spiked sample and CSA/decorin competitive assay including chondroitinase-treated cancer cell line or plasma samples." (PMID 36746966, 2023). "In addition, the binding of recombinant VAR2CSA to cancer cells (SW480), patient plasma, or decorin is abolished if the samples were treated with chondroitinase before binding analyses, indicating the specific binding of recombinant VAR2CSA." (PMID 36746966, 2023). "Therefore, and because of its capability to inhibit cancer growth by sequestrating TGF-β, decorin has also been described as “the guardian from the matrix”." (PMID 34917515, 2021). "Collectively, these results suggest that decorin may act as a natural antagonist of the IGF1R and IR-A in bladder and other types of cancer where these receptors might play a critical role." (PMID 33673232, 2021). "Reduced expression or total absence of DCN has been observed in various forms of human cancers, including HCC." (PMID 33809195, 2021). "In addition, the levels of FGFBP1, DCN, FUR, and CXCL9 differed significantly between the benign and cancer groups by univariate analysis (ANOVA)." (PMID 30019538, 2018). "MMP2, IGF2, DCN, LUM and TWIST are involved in proteoglycans in cancer pathway." (PMID 30576338, 2018). "The second contributor to the signature was the matrix protein decorin (DCN), a proteoglycan highly expressed in stroma but not in cancer (Järvinen and Prince, 2015)." (PMID 30019538, 2018). "Furthermore, DCN has been reported to obstruct EGFR function and trigger apoptosis via caspase-3 activation, which leads to inhibition of in vivo cancer growth." (PMID 29100340, 2017). "Cancer cells treated with RdB/DCN or RdB/IL12/DCN efficiently expressed DCN, whereas no expression was observed in the RdB-treated or RdB/IL12-treated groups." (PMID 28002796, 2017). "However, recent studies have shed light on newly identified tissue-specific properties of both DCN and LUM in normal tissues and in the malignant cancer microenvironment." (PMID 26230845, 2015). "The aim of this study was to determine whether the SLRPs decorin (DCN) and lumican (LUM) are recruited in cell plasticity and microenvironmental adaptation of differentiated cancer cells induced towards stem-like phenotype." (PMID 26230845, 2015). "In addition, we investigated the effect of decorin and CAF-derived matrices on cancer cell adhesion." (PMID 25593993, 2014). "Altogether, these findings indicate that cancer cells attach to type I collagen, but they are not able to attach to decorin as a single substrate." (PMID 25593993, 2014). "Cancer cells were seeded onto matrices with or without decorin coating, and MTT and SRB adhesion assays were carried out after 24h incubation." (PMID 25593993, 2014). "The GeneSapiens database revealed that decorin is expressed at marked levels in almost all different types of human epithelial carcinoma tissue samples in vivo (data not shown)." (PMID 24146840, 2013). "Four genes (DAB2, DCN, CELF2 and COL1A2) have appeared previously in cancers." (PMID 22867264, 2012). "Decorin is a functional component of the ECM, and is also considered to be a novel biological ligand for EGFR, which is frequently expressed at elevated levels in multiple cancers of epithelial origin." (PMID 20092659, 2010). "Decorin, a muscle cell-specific cytokine released from myocytes in response to stress, was significantly enriched in C2C12-EVs and may contribute to C2C12-EVs’ inhibitory activity on cancer cells." (PMID 41300368, 2025).
cancer (continued). "While EVs have been identified as delivery vehicles for some myokines, EV-mediated transport of decorin has not been assessed to date but may play roles in cellular mediation in cancer communication as well as in anti-cancer processes." (PMID 41300368, 2025). "Moreover, specific DCN knockdown in breast fibroblasts modulated the expression/secretion of several CAF biomarkers and cancer-promoting proteins (α-SMA, FAP- α, SDF-1 and IL-6) and enhanced the invasion/proliferation abilities of these cells through activation of the STAT3/AUF1 signaling." (PMID 38667295, 2024). "There have been no published studies on the influence of decorin and cancer in the dog." (PMID 37104411, 2023). "YKL-40 gene expression was primarily increased in the fibroblast (gene annotation: COL1A, BGN, DCN), myeloid (gene annotation: CD68, LYZ, AIF1), cancer (gene annotation: EPCAM, KRT7, KRT18), and B-cell (gene annotation: CD79A, CD79B) populations in cancer tissue compared to healthy tissue." (PMID 35631632, 2022). "Furthermore, levels of DCN and CXCL9 also differed between cancer subtypes." (PMID 30019538, 2018). "Also our yet unpublished studies with testis-derived GTCs support the notion that decorin expression by cancer cells is predominantly absent." (PMID 28653173, 2017). "In addition, DCN can inhibit the interactions between the ECM and cancer cells." (PMID 29100340, 2017). "Cancer cell adhesion was inhibited by decorin, but not by CAF-derived matrices." (PMID 25593993, 2014). "Especially, there has been some uncertainty whether different cancer cells express decorin in addition to non-malignant stromal cells." (PMID 24146840, 2013). "The cancer cells were also negative for decorin immunoreactivity." (PMID 24146840, 2013). "That is, DCN is expressed by the cancer-transformed myoepithelial cells, and not by the normal." (PMID 22719844, 2012). "Importantly, decorin has emerged as a promising anti-cancer agent produced by normal cells." (PMID 30813947, 2019). "Thus, CAR-targeted DCN could also be useful in the treatment of other conditions outside of cancer and healing wounds in which nontargeted DCN has shown activity and where there is angiogenesis or inflammation affecting nearby vasculature." (PMID 26697491, 2015). "Indeed, no decorin mRNA could be detected in benign epithelial cells or in malignant cancer cells of the human breast." (PMID 23007289, 2013). "However, there is some uncertainty whether different cancer cells express decorin in addition to non-malignant stromal cells." (PMID 24146840, 2013). "Importantly, the fact that we did not detect any mRNA of cancer‐specific genes (AZGP1 and KRT19), nor of CAF‐specific genes (LUM and DCN), confirmed the absence of non‐endothelial RNA contamination." (PMID 40348600, 2025). "We discovered that decorin evoked growth inhibition in vitro, enhanced apoptosis and blocked EGF- and FGF-mediated evasion from Matrigel (not shown), indicating that decorin exerts similar inhibitory activity on EGFR and Met dependent pathways as shown for other carcinoma cells." (PMID 23029096, 2012). "Therefore, the lack of decorin favors ECM disruption, the swelling of fibrils as well as the development of stiff very large-diameter fibrils which favor adhesion and traction of the invading cancer cells." (PMID 40643556, 2025).
infection (19 papers, 2008 to 2023). The state of being infected such as from the introduction of a foreign agent such as serum, vaccine, antigenic substance or organism. "Overall the VR-2332 infection appeared to upregulate genes that favored the M2 response, as well as, causing upregulation of DCN and other proteoglycans against the various mediators." (PMID 28727780, 2017). "B. burgdorferi selectively colonizes decorin-rich heart microenvironments such as the tunica adventitia, and upon infection, decorin-deficient mice harbor fewer B. burgdorferi in the heart than do littermate control mice." (PMID 25079227, 2014). "Of note, DbpA ́s interaction partner decorin is highly expressed in the skin and joints, two major sites of infection in the context of Lyme disease." (PMID 34206480, 2021). "They discovered that several small leucine rich proteoglycan (SLRP) family members, including biglycan, decorin, fibromodulin and osteoadherin, contain inherent anti-microbial properties that can eradicate infection." (PMID 33543032, 2020). "Infection of human monocytes with S. pyogenes results in decorin expression, akin to previous findings." (PMID 33543032, 2020). "At the inoculation site at three days post-infection, production of DbpAPBr, which displayed greater decorin- and dermatan sulfate-binding activity than DbpAVS461 or DbpAN40-D10/E9, conferred approximately six- to nine-fold greater colonization (P<0.05)." (PMID 25079227, 2014). "As an extracellular bacterium, B. burgdorferi resides primarily in the ECM and connective tissues, and between host cells during mammalian infection, where host ligands for both DbpA and DbpB, including decorin and glycosaminoglycan, are abundantly present." (PMID 18833332, 2008). "Moreover, the expression amounts of tendon‐related proteins, such as collagenase type 1 (Col1a) and decorin (DCN) were increased to promote efficient tendon repair with minimal infection." (PMID 37323624, 2023). "In mice, Borrelia loads were increased in these tissues with high decorin expression, promoting symptomatic manifestations, and spirochetes could still be recultivated from joint punctates 15 weeks after infection." (PMID 34206480, 2021). "Notably, transcripts encoding several structural elements of ECM, such as fibronectin, collagen chains, laminin, and proteoglycans (BGN, DCN), were downregulated, suggesting impaired tissue repair and wound healing cascades at the infection site." (PMID 32244468, 2020). "Furthermore, in the same study, expression of decorin was detected mainly in demyelinating areas starting at 56 days post infection." (PMID 27441688, 2016). "Binding of DbpA and DbpB to decorin is important for infection and dissemination in the host." (PMID 26371761, 2015). "The expression heatmaps of the endothelial cell genes in the sample revealed that DCN and IFN-activated endothelial cell marker genes (Irf8, Rsad2, Ifit1, Ifit3, Iigp1) were significantly upregulated at 1 month post-infection as compared with the WT group." (PMID 36569953, 2022). "Genes coding for the ECM proteins fibronectin (fn1) and decorin (dcn) were highly expressed in the dura mater; however, expression levels were not altered in response to infection." (PMID 33524035, 2021). "Because the activation of this network of DAMPs leads to M1 innate immune responses, the down regulation of BGN, DCN, and VCAN during infection could effectively hinder the stimulation of the M1 (pro-inflammatory) mediators used in the current study." (PMID 28727780, 2017). "The study was further limited by the fact that we were unable to evaluate decorin levels in the weeks of delivery in the PTB and control groups, and that no investigation was made into the presence of infection." (PMID 36415257, 2022).
kidney disease (8 papers, 2011 to 2025). "The uncontrolled regulation of ECM components, such as collagens, proteoglycans, and glycoproteins (e.g. agrin, decorin, versican, biglycan, and laminins), has been described in numerous kidney diseases." (PMID 40524147, 2025). "TGF-β1 blockade by different approaches, including neutralizing antibodies, siRNAs, or blockers such as decorin, inhibited fibrosis both in vitro and in experimental renal disease." (PMID 26074680, 2015). "But, DCN is absent in chronic glomerulosclerosis and interstitial fibrosis in renal diseases." (PMID 22279542, 2012).
cardiovascular disease (7 papers, 2018 to 2024). "Additionally, Metrnl, which is arecently discovered secreted protein, is promising as a new biomarker for CHD.Furthermore, the roles of potential biomarkers of CVD, such as DCN and myonectin,in predicting cardiovascular disease and poor prognosis need to be furtherexplored." (PMID 39077334, 2024). "SLRPs, including LUM, BGN, and DCN, are all crosslinking regulators and are shown to play a role in ECM remodeling and fibrosis in different mouse models of muscular and cardiovascular diseases." (PMID 38130476, 2023). "DCN is a leucine-rich proteoglycan constituent of the ECM and has powerful antifibrotic, antioxidant, anti-inflammation, and antiangiogenic properties in cardiovascular diseases." (PMID 34141473, 2021).
connective tissue disorder (6 papers, 2018 to 2025). A disease involving the connective tissue. "Since proteoglycans like decorin and glycosaminoglycans (GAG) can influence formation of the microfibrillar network and human connective tissue disorders have been linked to defects in GAG synthesis the decorin changes possibly also contribute to the elastic fiber reduction." (PMID 39680136, 2024).
breast (3 papers, 2020 to 2024). "Subsequently, we investigated whether excessive decorin production may attenuate metastasis formation in the liver and whether decorin may act as a physiological inhibitor of RTKs in liver metastases." (PMID 32824864, 2020).
myopathy (3 papers, 2021 to 2024). A disease of the muscle in which the muscle fibers do not function properly. "Further investigation may be required for more understanding of the mechanisms of myopathy phenotype caused by decorin-proteoglycan with CS side chain." (PMID 34708033, 2021). "The composition of macromolecules in IMCT, including hydroxylysyl pyridoxine cross-linking, decorin and glycosaminoglycans, were increased with the severity of WB myopathy." (PMID 38397484, 2024). "In the present study, we investigated the effects of decorin on spatial distribution and expression in myopathy using Chst14–/– mice as an mcEDS model." (PMID 34708033, 2021). "The functional alteration by decorin-proteoglycan in Chst14–/– mice might lead the myopathy phenotype in the muscle." (PMID 34708033, 2021). "Considering these results, the myopathy phenotype in Chst14−/− and mcEDS may be caused by connective tissue fragility in the skeletal muscle associated with ECM functional changes, including changes in decorin localization and pathological activation." (PMID 34850861, 2021). "Particularly, WB myopathy increases the contents of major IMCT components (collagen, HP cross-link, decorin and GAGs) and alters thermal stability and the secondary structure of IMCT, which contribute to the elevated shear force value and hardness of meat." (PMID 38397484, 2024). "Therefore, the loose meshwork of fibers might be associated with the myopathy phenotype in Chst14–/– mice, and mcEDS may be caused by connective tissue fragility in the skeletal muscle, associated with ECM functional changes including ectopic localization of decorin." (PMID 34708033, 2021).
genetic disease (2 papers, 2018 to 2023). "Interestingly, besides the “DCN” locus, three other loci harbour genes implicated in Mendelian diseases including rare connective tissue, inflammatory and eye disorders with corneal thinning as one of their clinical features, giving weight for them to be prioritized in follow-up studies." (PMID 29760442, 2018).
Metabolic Disorder (2 papers, 2020 to 2023). "Physical inactivity increases the risk of metabolic diseases as it leads to the release of specific muscle-derived cytokines, such as myonectin, irisin, brain-derived neurotrophic factor (BDNF), and decorin." (PMID 38136166, 2023). "Studies have demonstrated the protective effects of decorin on glucose metabolism, which may suggest it has a role in reducing metabolic disorders correlated with an excessive amount of AT." (PMID 38136166, 2023). "Collectively, the metabolic disorder of ECM mediated by DCN may play an important role in the formation of dBAVMs." (PMID 33364932, 2020).
retinopathy (2 papers, 2022 to 2023). "In another study, decorin treatment in rats with oxygen-induced retinopathy inhibited retinal neovascularization by reducing neovascular endothelial cell proliferation and the immunoreactivity of VEGF and TNF-α in the retina." (PMID 36611867, 2022). "A decreased expression of decorin has been reported in the retina of animal models of ischemic disease in the retinal vessels, such as oxygen-induced retinopathy in rats." (PMID 36611867, 2022).
skin disorder (2 papers, 2020 to 2025). Any deviation from the normal structure or function of the skin or subcutaneous tissue that is manifested by a characteristic set of symptoms and signs. "DCN exhibits both anti-angiogenic and anti-fibrotic properties, and previous studies have shown that genetic deletion or pharmacological inhibition of GzmB can prevent DCN cleavage and increase DCN levels in several skin disorders." (PMID 41310732, 2025). "Namely, cleaved DCN is found in many skin disorders, and many proteases are known to cleave DCN." (PMID 32497513, 2020).
degenerative diseases (1 paper, 2021). "Decorin is known to play a critical role in regulating microvasculature during development and degenerative diseases in the retina." (PMID 34947953, 2021).
osteoarthropathy (1 paper, 2020). "Decorin is a member of small leucine-rich proteoglycan family, which is involved in multiple biological functions mainly as a structural and signaling molecule, and disturbances in its own metabolism plays a crucial role in the pathogenesis of osteoarthropathy." (PMID 32353084, 2020).
DCN also shares sentences with these, for which no sentence is quoted: multiple myeloma (5 papers); acute myocardial infarction (3); cardiac diseases (3); angiosarcoma (2); basal cell carcinoma (2); cardiomyopathies (2); cervical cancer (2); Duchenne muscular dystrophy (2); gestational diabetes (2); hypertrophy (2); idiopathic pulmonary fibrosis (2); Infertility (2); leiomyoma (2); Li-Fraumeni syndrome (2); localised scleroderma (2); lung diseases (2); myxofibrosarcoma (2); periodontitis (2); psoriasis (2); type 1 diabetes (2); abortion (1); acute coronary syndrome (1); acute respiratory distress syndrome (1); adenocarcinoma (1); age (1); Alport syndrome (1); Anxiety (1); arterial tortuosity syndrome (1); atopic asthma (1); autosomal dominant cutis laxa (1).
A further 92 diseases each share a sentence with DCN in 1 paper.